CTNNB1 (catenin beta 1)
Diseases named in the same sentence as CTNNB1 in open-access papers (continued):
Sharing a sentence is not in itself a finding about the gene and the disease.
tumor (continued). "One tumor (2.8%) displayed the well-known T41A CTNNB1 gene mutation." (PMID 34725446, 2022). "Thus far, most human neoplasms with frequent CTNNB1 mutations are relatively low-grade with relatively favorable prognosis, such as desmoid tumor, renal angiomyolipoma, pulmonary lymphangioleiomyomatosis, and pancreatic solid pseudopapillary tumor." (PMID 36428715, 2022). "Based on the frequency of CTNNB1 mutated tumours in NSMP group (26–52%) with independent prognostic value, some authors propose CTNNB1–mutated ECs may be regarded as a fifth molecular subgroup." (PMID 35531470, 2022). "Here, we hypothesized that ctDNA may be the surrogate marker of tumor mutation profiles including CTNNB1 mutation, and might predict the response to immunotherapy." (PMID 35884434, 2022). "DANCR (Anti-differentiation noncoding RNA) is higher-expressed in stem-like HCC cells and facilitates the oncogenesis and intrahepatic/extrahepatic tumor colonization by associating with and liberating CTNNB1 mRNA from the repressing effect of CTNNB1-targetive miRNAs." (PMID 35871161, 2022). "Thus the high-level β-catenin activity observed in all EdarTg951/951 tumours can be explained by their independent, but functionally identical, somatic mutations in CTNNB1." (PMID 34916592, 2022). "Driving somatic mutations were detected in Ctnnb1 and Kras in the liquid biopsies of early stages of tumor development, corresponding to the formation of aberrant crypt foci, the first histological alterations that can be identified throughout the formation of CRC." (PMID 36313038, 2022). "Furthermore, we have pathologically evaluated the prevalence of tumor-infiltrating lymphocytes (TILs) and PD-L1 expression level based on CTNNB1 somatic mutation." (PMID 34986867, 2022). "In addition, more than two different mutations in Ctnnb1 were found in 14 out of 20 tumor samples (70%) showing polyclonality in this model." (PMID 36313038, 2022). "CTNNB1 is an oncogene whose hyperactivation is associated tumor progression in HCC." (PMID 36339710, 2022). "Additionally, whole-exome sequencing, in the context of tumor cells extracted from the surgically resected specimen, revealed that CTNNB1 and NFE2L2 mutations were the significant oncogenic mutations." (PMID 35382169, 2022). "Interestingly, we found that the mRNA expression levels of DPP4/CTNNB1/MET are inversely associated with tumor purity." (PMID 35205190, 2022). "Thus, we proposed a novel stratification model consisting of three categories instead of four, by merging the 2020 Classifier high risk group with CTNNB1 mutated tumours." (PMID 35205661, 2022). "Tumor formation could be initiated upon a loss-of-function (LOF) mutation of APC or a gain-of-function (GOF) mutation of CTNNB1, leading to gene expression, proliferation, and cell cycle progression in the absence of Wnt." (PMID 36457029, 2022). "Identifying mutational status of the CTNNB1 gene, especially in low-grade tumours, is important for more accurate risk stratification of patients and could potentially lead to better management of women." (PMID 35531470, 2022). "Based on the presence of CTNNB1 mutations in mammary AcCC, this tumor may be closer to the pancreatic counterpart than to the salivary-type malignancy or TNBC." (PMID 36332545, 2022). "In this study, hot spot mutations of CTNNB1 have been detected at Ser33, Ser37, Thr41 and Ser45 by droplet digital polymerase chain reaction (ddPCR) using circulating tumor DNA (ctDNA) of patients with HCC, and their relationship with ATZ/BV treatment response and prognosis has been investigated." (PMID 35711837, 2022). "Comparison of CTNNB1 mutation between the original tumor and the associated derived cell line was done using Sanger sequencing as the primary method; this helped to also differentiate desmoid tumor cells from fibroblasts." (PMID 36240209, 2022). "Mutations of CTNNB1 have also been associated with tumours in younger patients." (PMID 35531470, 2022).
tumor (continued). "HCCs with CTNNB1 mutations appear morphologically heterogeneous, although nuclear increase of β-catenin in HCCs has been associated with Ki67 expression, reflecting its role in promoting tumor proliferation." (PMID 35454818, 2022). "Prior to cfDNA analysis, we evaluated the sensitivity of E-ice-COLD-PCR and endpoint PCR followed by next generation sequencing (NGS) to detect mutations in Ctnnb1 and Kras in 5 tumor samples (mice: M1, M3 M8, M10 and M16) previously analyzed with Sanger sequencing." (PMID 36313038, 2022). "Therefore, if the excised tumour is small in size, we need to know that β-catenin immunostaining is indicative of the presence of CTNNB1 mutation, particularly in the case of recurrent tumours." (PMID 33914771, 2021). "A high-throughput sequencing of the tumor described in both cases alteration in the Wnt/β-catenin pathway: a mutation in CTNNB1 (exon 3, c.110C>G, p.S37C, reported as a hotspot in COSMIC) in one case and a homozygous loss associated with breakage targeting APC (5q22.2) in the second." (PMID 33796447, 2021). "CTNNB1 mutations in exon 3 are associated with enrichment of the Wnt signalling pathway, and may characterise a subset of aggressive tumours associated with younger age and earlier stage." (PMID 34830795, 2021). "Surprisingly, the percentage of CTNNB1-mutated tumours is lower (8.7%) than that described in previous series; however, we could not find any reason that could explain these discrepancies." (PMID 34420090, 2021). "Interestingly, all tumours with CTNNB1 exon 3 hotspot mutations in our series were DNA MMR-proficient." (PMID 34420090, 2021). "Moreover, in the TCGA study, 53% of tumours in the copy-number low and 19% in the microsatellite instability (hypermutated) categories harboured mutations in the CTNNB1 gene." (PMID 34420090, 2021). "The CTNNB1 genes encode β-catenin protein, which support tumor growth." (PMID 34836311, 2021). "According to whether CTNNB1 was mutated, 374 tumour tissues were divided into two groups, among which 98 were mutated and 276 were not mutated." (PMID 33300278, 2021). "Thus, there were 6 patients (31.6%) who developed tumour relapse in the CTNNB1-mutated group compared with 21 patients (10.6%) in the CTNNB1 wild-type group (p = 0.018)." (PMID 34420090, 2021). "We hypothesized that the combined analysis of ctDNA and tumor tissue DNA may provide a more complete picture of the frequency of CTNNB1 mutation." (PMID 33827453, 2021). "This fact reinforces that CTNNB1-mutated tumours may be considered a fifth group of intermediate prognoses among low-grade, early-stage EECs, apart from already established TCGA molecular groups." (PMID 34420090, 2021). "Only one tumour with CTNNB1 exon 3 mutation showed a MELF pattern of myoinvasion." (PMID 34420090, 2021). "Among the CTNNB1-mutation-positive patients with available matched pre- and post-operative urine (n = 13), nine showed apparent elimination (n = 7) or severalfold reduction (n = 2) of the mutation in urine following tumor resection." (PMID 34441409, 2021). "To investigate if HOXB9 can promote tumour formation we bred Sf-1:Hoxb9 mice with mice containing the activating conditional Ctnnb1 deletion allele and a construct with Cre recombinase driven by Cyp11a1-regulatory sequences (Ctnnb1 mutant mice, referred to as ABC)." (PMID 33214683, 2021). "This CTNNB1 gene mutation has been associated with the inflammatory subtype of tumor hepatocytes, which is characterized by an over expression of acute phase inflammatory proteins like CRP and serum amyloid A (SAA) and the consequent constitutive activation of the IL6/JAK/STAT pathway." (PMID 34503196, 2021).
tumor (continued). "As a summary of these preliminary findings, mutations associated with Wnt/β-catenin activation were detected in the tumor DNA of four patients, with three being CTNNB1 mutations and one being a mutation involving the guanine nucleotide binding protein-alpha stimulating sub-unit (GNAS) gene." (PMID 33553649, 2021). "In contrast, tumours with CTNNB1 exon 3 mutation are prone to develop tumour recurrence." (PMID 34420090, 2021). "Further investigation is required to determine whether immunohistochemical staining for β-catenin in different specimen types and in varying tumour sizes is indicative of mutations in the CTNNB1 gene." (PMID 33914771, 2021). "In our series, all tumours with CTNNB1 exon 3 mutation were DNA MMR-proficient." (PMID 34420090, 2021). "We demonstrated that CTNNB1 mutation correlates with nuclear β-catenin expression in larger or excised DF tumours, therefore caution is advised in the interpretation of the immunohistochemical and mutation data when derived from biopsied samples or small tumours." (PMID 33914771, 2021). "Once a homozygous WT1 mutation is present, the cells may be independent for an additional CTNNB1 mutation and could be the seeds for tumor development." (PMID 33379206, 2020). "Thus, we performed association investigations between the levels of serum tumor markers and SNP of the CTNNB1: rs1880481." (PMID 32453708, 2020). "One case harbored two somatic CTNNB1 mutations, both in different tumor nodules." (PMID 31598872, 2020). "Correlating the individual CTNNB1 mutational status and tumor site, we observed a significantly higher incidence of deleterious T41 alterations in intra-abdominal compared to abdominal and extra-abdominal DTF cases (n = 43/59; 72.9% vs. n = 63/125; 50.4%; p = 0.0042)." (PMID 32099073, 2020). "CTNNB1 (β-catenin) is a key protein of Wnt signals and linked to the development of tumor." (PMID 32211321, 2020). "For instance, higher CTNNB1 mutation frequency in male-derived tumours may simply be due to more mutations occurring in those same samples." (PMID 32859912, 2020). "Higher levels of intracellular CTNNB1 are associated with a higher tumor grade and poor prognosis." (PMID 32083079, 2020). "Searching for our mutated genes in the large pediatric cancer databases PECAN and PedcBioPortal (any tumor) revealed CTNNB1 as the most commonly mutated gene, followed by DEPDC5 (several variants were identified in 12 types of pediatric tumors) in PECAN, and FRMPD1 in PedcBioPortal." (PMID 32432034, 2020). "It has been shown that CTNNB1 exon 3 mutations are associated with an aggressive phenotype in several of these tumor types and may be associated with therapeutic tolerance." (PMID 32651460, 2020). "These genetic variants led to the accumulation of the CTNNB1, a hallmark of tumor development." (PMID 31699039, 2019). "This supports the notion that CTNNB1 mutations in APAs drive proliferation and tumour growth." (PMID 31000732, 2019). "However, the small number of tumours (and in particular with CTNNB1 mutations) means that these results should be considered with caution." (PMID 31000732, 2019). "These genetic variants led to the accumulation of CTNNB1, a hallmark of tumor development." (PMID 31699039, 2019). "Amongst tumours with CTNNB1 missense mutation, one harboured gain and three harboured cnLOH." (PMID 29872083, 2018). "We present here a method of detection of DT specific CTNNB1 mutations using a targeted strategy ddPCR on cfDNA extracted from blood samples and the correlation of total plasmatic cfDNA concentration with evolution of the tumor." (PMID 29719606, 2018). "Interestingly, tumor nuclear CTNNB1 expression seemed to be associated with higher mortality among older, but not among younger patients." (PMID 29652830, 2018).
tumor (continued). "Next, we aimed to further dissect the molecular signatures obtained from the RNA-Seq data and establish if these correlated with particular tumour characteristics including diagnosis, percentage of tumour content, CTNNB1 mutation allele frequency and the presence of specific histological features." (PMID 29541918, 2018). "Furthermore, although the primary tumor carried a CTNNB1 mutation, the cells cultivated in WT medium were wild type." (PMID 29542868, 2018). "Predictive factors have been described, such as age, tumor localization, and CTNNB1 mutations." (PMID 30034268, 2018). "Direct measurement of CTNNB1 mRNA (encoding β-catenin) from transfected tumour spheroids confirmed a transient but significant knockdown of β-catenin when siRNA:liposome complexes were formed with serum, but not when prepared in the presence of reduced-serum media (Opti-MEM)." (PMID 29785035, 2018). "So far, the effect of CTNNB1 mutation on tumor behavior is controversial." (PMID 30274313, 2018). "We identified CTNNB1 mutations in 26 (93%) of 28 WNT tumours (appendix pp 5–6)." (PMID 30392813, 2018). "Therefore, the lung metastasis and its derived cell culture were originated from a clone of cells within the primary tumor that carried the homozygous p.S45Δ mutation, whereas the bulk primary tumor DNA was heterozygous for another CTNNB1 mutation." (PMID 29542868, 2018). "Owing to APC and CTNNB1 mutations, β-catenin signaling is hyperactivated, and several downstream targets of β-catenin, such as c-myc, cyclin D1, and PPARdelta, have been identified as markers of tumor development." (PMID 30275459, 2018). "Plotting of normalised expression levels confirmed the relationship of these brown module genes with CTNNB1 mutation allele frequency, further supporting that expression of these genes is enriched within the tumour cells (r = 0.83, 0.95, 0.96 respectively for each gene, p < 1 × 10−5) [Suppl." (PMID 29541918, 2018). "Missense mutations in exon 3 of CTNNB1, c.133T > C (p.S45P), c.104T > A (p.I35N), c.136C > A (p.S45Y), c.109C > G (p.S37C), c.105G > A (p.G34R) and c.134C > T (p.S45F) were found in 6 individual tumours, whereas exon 5 was devoid of any mutation." (PMID 29872083, 2018). "Are the Ctnnb1 mutations present in all tumor cells in human ACP?" (PMID 28414891, 2017). "As expected, all tumours with CTNNB1 mutations (n = 14) were classified as WNT." (PMID 29044166, 2017). "CTNNB1, encoding β-catenin, is a well-known tumor-related gene in the wnt signaling pathway." (PMID 28963373, 2017). "Evidence also suggests that HPGD (15-PDGH) expression levels in normal colon and the germline rs6983267 polymorphism that relates to tumor CTNNB1 (β-catenin)/WNT signaling status may predict the efficacy of aspirin for cancer chemoprevention." (PMID 29552640, 2017). "Phylogenetic analysis of the clonal structure in this tumour revealed that all 3 CTNNB1 mutations were in three separate subclones, providing strong evidence for parallel evolution leading to activation of the Wnt/β-catenin pathway in this tumour." (PMID 28961847, 2017). "At the somatic level, we found a CTNNB1 hotspot mutation and chromosome 1q gain in the tumor." (PMID 29190888, 2017). "Both the primary tumor and recurrence showed the same CTNNB1 mutation." (PMID 26927026, 2016). "In addition the same tumor harbored different CTNNB1 mutations in different histological areas (unpublished observation)." (PMID 27213811, 2016). "This hypothesis could explain the extensive intratumoral heterogeneity in ACP and perhaps the difficulty we and others have found in obtaining “pure” tumor samples to accurately identify CTNNB1 mutations." (PMID 25990246, 2015).
tumor (continued). "The relatively low Wnt signaling activity of hepatocytes may form a tumor suppressor barrier, providing the selective pressure underlying the high frequency of activating CTNNB1 mutations in this subtype." (PMID 25738607, 2015). "Differential expression analysis was beyond the scope of this study, however variability was expected in these samples since they represent different tumour types and CTNNB1 mutation status and it is likely that other associated molecular changes would be variable among them." (PMID 26039282, 2015). "This is a possible mechanism by which reduction of CTNNB1 expression by PPARγ agonists could contribute to inhibition of the loss of cellular attachments, as well as reducing the transcription of tumor-promoting target genes of CTNNB1 such as CCND1 and MYC." (PMID 24672773, 2014). "More importantly, we identified certain molecular events which may promote tumorigenesis in a CTNNB1 mutation-positive tumor." (PMID 24798046, 2014). "This tumor type is ideal for this purpose because it is characterized by a monotonous composition with a neoplastic cellularity of about 70–80% and has a molecular hallmark consisting of a heterozygous CTNNB1 mutation." (PMID 25127237, 2014). "The tumor grew from the transverse mesocolon, and harbored a mutation of the CTNNB1 gene." (PMID 23575352, 2013). "We report here the development, validation, and clinical implementation of a multiplexed assay designed to simultaneously detect 43 recurrent mutations in BRAF, KIT, NRAS, GNA11, GNAQ, and CTNNB1 using tumor-derived DNA from formalin-fixed paraffin-embedded (FFPE) tissues." (PMID 22536370, 2012). "The number of CTNNB1 mutated tumours was too low for any correlation." (PMID 21901162, 2011). "CTNNB1 mutations may represent such an early event, which may be conditional for the entire sequence of subsequent events during tumor progression." (PMID 21760996, 2011). "This tumour did display high nuclear staining of CTNNB1, suggesting that the mutation could be the cause of pathway activation in this sample." (PMID 19293793, 2009). "DNA was available for CTNNB1 mutation analysis in 48 of 54 HB tumours." (PMID 19034281, 2008). "Moreover, in tumours displaying microsatellite instability, mutations the CTNNB1 gene were more frequent." (PMID 16356174, 2005). "This may indicate that these proximal colon tumours, which often also show mismatch repair deficiency, are more likely to harbour CTNNB1 mutations." (PMID 16356174, 2005). "However, many of the tumours rescued 10 days after ENU treatment still contained Ctnnb1 mutations." (PMID 41339549, 2026). "Moreover, the results of our study suggest that tumors with CTNNB1 mutation and GREB1::CTNNB1 fusion may exhibit identical morphology and potentially represent the same category of tumor." (PMID 41606383, 2026). "Moreover, the significant co-occurrence of TERTp and CTNNB1 exon 3 mutations suggests a possible synergistic role in tumour progression, pointing to distinct molecular pathways that could be exploited for therapeutic intervention." (PMID 40650279, 2025). "Therefore, more research is needed to determine whether CTNNB1 mutations and Wnt/β-catenin activation affect tumour phenotypes and patient prognosis." (PMID 41142820, 2025). "In addition to the constitutional and somatic DICER1 oncogenic variants, the somatic CTNNB1 p.(Thr41Ala) oncogenic variant was also identified in the present tumor, which also justified its histopathogenic relationship with the family of tumors containing CD10-positive morulae." (PMID 40892116, 2025). "Additionally, functional studies—such as patient-derived organoids and single-cell sequencing—are essential to elucidate the biological impact of SMAD2, ERBB4, ALK, and CTNNB1 mutations and their roles in tumor heterogeneity, drug resistance, and immune evasion." (PMID 40869017, 2025).